MMP2 (matrix metallopeptidase 2)
Diseases named in the same sentence as MMP2 in open-access papers (continued):
Sharing a sentence is not in itself a finding about the gene and the disease.
renal carcinoma (29 papers, 2012 to 2025). A carcinoma arising from the epithelium of the renal parenchyma or the renal pelvis. "Research on renal carcinoma cells revealed that sunitinib not only decreased MMP-2 and MMP-9 activity but also suppressed the expression of EMT markers." (PMID 39968177, 2025). "The role of MMP-2 was also suggested in renal carcinoma; however, the exact role seems to depend on the stage of the carcinogenic process, showing how multifaced the role MMP-2 has." (PMID 39769454, 2024). "The exogenous knockdown of JAM3 has been shown to inhibit renal carcinoma cell migration and promote renal carcinoma cell apoptosis via regulation of E‐cadherin, N‐cadherin, integrin β1 and MMP2 expression." (PMID 38124399, 2024). "Phosphorylated CREB can promote the invasive metastasis of renal cancer by regulating the expression of matrix metallopeptidases (MMP2 and MMP9) and EMT‐related proteins." (PMID 39092291, 2024). "Cell cycle arrest can be induced by LGK974 by downregulating cyclin D1, c-Myc, MMP9, and MMP2 in renal cancer cells." (PMID 37763649, 2023). "Collectively, these results indicate that the IL6-increased STAT3 activation and MMP2 expression in renal cancer cells can be antagonized by concomitant administration of anti-IL6 antibody." (PMID 31636361, 2020). "In particular, HIF-1α exclusively regulates glycolytic gene expression, whereas HIF-2α has been shown to promote tumor growth in a renal carcinoma xenograft model and invasiveness (through up-regulation of MMP-2, MMP-9, and PAI-1)." (PMID 31817100, 2019). "Hsa-miR-129-2-3p, which strongly reduced anchorage independence as well, was previously shown to reduce the levels of phosphorylated FAK protein and MMP2 and 9 proteins in renal carcinoma cells." (PMID 27270309, 2016). "The current study measured the content of MMP-2 and -9 and TIMP-1 and -2 in the sera and urine of patients with kidney carcinoma by enzyme-linked immunosorbent assay." (PMID 24520285, 2014). "Similarly, JAM3 was found highly expressed in renal carcinoma cells, inhibited tumor cell apoptosis, and promoted cell migration by upregulating levels of N-Cadherin, integrin β1, and MMP-2." (PMID 38400838, 2024). "Also, resveratrol treatment (25 μM, 50 μM, 100 μM) limited the proliferation, migration, and invasion of neoplastic cells in renal cancer by inhibiting MMP-2 and MMP-9 and stimulating TIMP-1 by modulating the MAPK/ERK and PI3 K/Akt pathways." (PMID 39335164, 2024). "The aim of the study was to analyze whether the expression of CD44, MMP-2, and MMP-9 in association with the histopathological subtype of RCC affects the survival of patients with renal cancer." (PMID 36831550, 2023). "Therefore, in this research, we answered the question of whether the immunohistochemical expression of CD44, MMP-2, and MMP-9 in association with the histopathological subtype of RCC affects the survival of patients with renal cancer." (PMID 36831550, 2023). "Hence, the aim of this study was to analyse whether the immunohistochemical expression of CD44, MMP-2, and MMP-9 in association with the histopathological subtype of RCC affects the survival of patients with renal cancer." (PMID 36831550, 2023). "On one hand, factors such as ACh can activate the cAMP/PKA/CREB pathway, leading to the upregulation of MMP2/9) and EMT‐related molecules, thereby promoting the proliferation, invasion, and metastasis of renal cancer cells." (PMID 39092291, 2024).
renal carcinoma (continued). "Specifically, NC reduced the level of phosphorylation of Akt and downregulated matrix metalloproteinase-2 (MMP-2) and MMP-9, leading to antimetastatic effects on renal cancer cells." (PMID 33288736, 2020). "We examined the expression of cytoplasmic β-catenin and Wnt target genes in renal cancer cells after treatment with LGK974, including the protein expression level of cyclin D1 and c-Myc and the RNA expression level of MMP9 and MMP2." (PMID 32104684, 2020). "TIMP-1 over-expression radio-sensitizes the renal cancer cells to gamma radiation and also shows elevation of TIMP-2 protein level as well as decrease of MMP-2 activity." (PMID 27659937, 2016). "Downregulation of forkhead box protein M1 reduced the expression and activity of MMP-2, -9 and VEGF, resulting in the inhibition of migration, invasion and angiogenesis of renal cancer cell lines." (PMID 24765179, 2014). "Likewise, EGCG at concentrations of 20 μM or more was found to inhibit, by about half, the expression and activity of MMP-2 and MMP-9 in human renal carcinoma cells (786-0 and ACHN) and thus reduce their migratory and invasive potential." (PMID 39335164, 2024). "In addition to interfering with the activity of transcription factors, EF-24 was shown to resensitize renal cancer cells to TNF-related apoptosis-inducing ligand (TRAIL)-induced apoptosis via reducing intracellular ROS production and MMP-2/MMP-9 activity." (PMID 36900342, 2023). "Next, we found that in renal cancer cells, overexpression of MKRN2 led to elevated β-Catenin phosphorylation and reduced β-Catenin protein expression, resulting in the attenuation of Wnt pathway that is marked by the down-regulation of signature genes (c-Myc, Cyclin D, Axin2, Bcl-2, MMP2, and MMP9)." (PMID 40959281, 2025). "An enhanced expression of VEGFR1 protein and VEGF and MMP2 genes in lung endothelial cells, and MMP9 gene in lung tissue was observed after treatment with rCSC-EVs, but not with EVs derived from non-stem renal cancer cells." (PMID 30872568, 2019). "Moreover, rCSC-EVs, but not those derived from non-stem renal cancer cells, were shown to carry several mRNAs of proangiogenic genes, such as VEGF, fibroblast growth factor 2 (FGF2), angiopoietin 1, ephrin A3, MMP2, and MMP911." (PMID 30872568, 2019).
renal cell carcinoma (29 papers, 2006 to 2026). "A recent study of renal cell carcinoma cells also demonstrated that POSTN overexpression increased the activity of MMP-2 and MMP-9." (PMID 35163164, 2022). "For instance, the overexpression of MMP-2 on the surface of renal cell carcinoma and membrane-type MMP-14 activity directly led to MICA shedding." (PMID 34502191, 2021). "Both MMP-2 and MMP-9 are implicated in angiogenesis which is critical for highly vascularized malignancies such as renal cell carcinoma." (PMID 31200666, 2019). "In terms of pathologic grade of renal cell carcinoma, the differences in MMP-2, MMP-9, MT1-MMP, TIMP-1, and TIMP-2 mRNA expression levels were not significant." (PMID 23281640, 2013). "In terms of tumor stage of renal cell carcinoma, the differences in MMP-2, MMP-9 and MT1-MMP mRNA expression levels were significant." (PMID 23281640, 2013). "Decrease in MMP2 expression mediated by VIP was also reported in renal-cell carcinoma." (PMID 34208590, 2021). "Lnc-216 and OSTM1-AS1 also upregulate MMP2 and MMP9 in retinal endothelial function and renal cell carcinoma respectively." (PMID 40457415, 2025). "In renal cell carcinoma, the PI3K/Akt/mTOR signaling pathway is activated to regulate the epithelial–mesenchymal transition process, and matrix metalloproteinase 2 (MMP2) and MMP9 are also involved." (PMID 38474114, 2024). "CD44, MMP-2, and MMP-9 are new potential molecular prognostic markers in renal cell carcinoma (RCC)." (PMID 36831550, 2023). "The study performed on renal cell carcinoma showed that the JAM3 gene is critical for its tumor migration ability via the regulation of genes coding for N-cadherin, integrin β1 (ITGB1) and MMP2." (PMID 35742950, 2022). "In summary, mean MMP-2, MMP-9, MT1-MMP, TIMP-1, and TIMP-2 mRNA expression in the renal cell carcinomas was significantly higher than in the normal renal tissue (P <0.05)." (PMID 23281640, 2013). "Mean MMP-2, MMP-9, MT1-MMP, TIMP-1, and TIMP-2 mRNA expression in the renal cell carcinomas was significantly higher than in the normal renal tissue." (PMID 23281640, 2013). "Mean MMP-2, MMP-9, MT1-MMP, TIMP-1, and TIMP-2 mRNA expression in the renal cell carcinomas was significantly higher than in the normal renal tissue (P <0.05)." (PMID 23281640, 2013). "In the present study, mean MMP-2, MMP-9, MT1-MMP, TIMP-1, and TIMP-2 mRNA expression in the renal cell carcinomas was significantly higher than in the normal renal tissue (P <0.05)." (PMID 23281640, 2013). "In this study, we examined the expression of MMP-2, MMP-9, membrane-type 1 (MT1)-MMP, TIMP-1, and TIMP-2 in renal tissue samples of renal cell cancer and examined the correlation between their expression and clinicopathological parameters." (PMID 23281640, 2013). "Adiponectin, via AdipoR1, inhibits mTOR through AMPK activation in renal cell carcinoma (RCC), suppresses vascular endothelial growth factor (VEGF), MMP-2 and MMP-9 and increases TIMP-1 and TIMP-2 secretion, resulting in decreased growth, dissemination and angiogenesis of RCC." (PMID 37686525, 2023). "In the present study, we examined the expression of MMP-2, MMP-9, MT1-MMP, TIMP-1, and TIMP-2 mRNA in human renal cell carcinoma tissues by a reverse transcriptase-polymerase chain reaction (RT-PCR) assay and examined the correlation between their expression and clinicopathological parameters." (PMID 23281640, 2013). "We focus on the specific role of MMP2, MMP7, and MMP9 in clear cell renal cell carcinoma (ccRCC) and major subtypes of RCC." (PMID 41893368, 2026). "In our study, mean MMP-2 and MMP-9 mRNA expression in the renal cell carcinomas was significantly higher than in the normal renal tissue (P <0.05), the levels of MMP-2 and MMP-9 mRNA expression were not correlated with tumor type or pathologic grade of renal cell carcinoma." (PMID 23281640, 2013).
renal cell carcinoma (continued). "It has been observed that exosomes derived from renal cell carcinoma (RCC) cells are enriched with carbonic anhydrase 9 (CA9), a downstream target of HIF‐α, and promote human umbilical vein endothelial cell (HUVEC) migration and tube formation through CA9‐mediated MMP‐2 upregulation." (PMID 36786037, 2023). "In contrast to other cancers such as renal cell carcinoma, we did not observe a correlation between JUNB, MMP2, and MMP9 expression, highlighting the dependency of JunB transcriptional programs on the tumor cell type." (PMID 34007044, 2021).
head and neck squamous cell carcinoma (28 papers, 2006 to 2025). A squamous cell carcinoma that arises from any of the following anatomic sites: lip and oral cavity, nasal cavity, paranasal sinuses, pharynx, larynx, and salivary glands. "Studies have shown that quercetin inhibits the migration and invasion of head and neck squamous cell carcinoma cells by suppressing the expression of MMP-2 and MMP-943." (PMID 38177197, 2024). "The FAK signaling pathway can regulate the expression of MMP-2, which inhibits the invasion of head and neck squamous cell carcinoma." (PMID 31783709, 2019). "The over-expression of MMP9 and MMP2 has been observed in head and neck squamous cell carcinomas patients presenting with lymph node involvement." (PMID 31579438, 2019). "Another example would be the upregulation of CD24 in microglial cells and MMP-2 in head and neck squamous cell carcinoma by granulocyte-macrophage colony stimulating factor (CSF2)." (PMID 21359202, 2011). "Our results suggest the importance of fibroblast-derived MT1-MMP and MMP-2 in head and neck squamous cell carcinoma cell invasion in vitro and tumor cell growth in vivo." (PMID 16515711, 2006). "Head and neck squamous cell carcinoma (HNSCC)—expressing high-integrin β1 was correlated with metastatic potential, a low survival in patients by modulating metalloproteinase-2 (MMP-2) activation." (PMID 33854965, 2021). "For instance, in head and neck squamous cell carcinoma (HNSCC), MMP9 and MMP2 exhibited a synergistic interaction that critically regulates tumor progression through coordinated modulation of cellular proliferation, migration, and invasive processes." (PMID 40666104, 2025). "Another study conducted an in vitro study examining the impact of α-mangostin on MMP-2 and MMP-9 expression in head and neck squamous cell carcinoma (HNSCC) cell lines (HN-22, HN-30, and HN-31)." (PMID 39595559, 2024). "Here, the same tendency in expression changes of TGM2, MMP2, CLDN7, HOXB7, and LCP1 can be found in different cancer types, including cervical and head and neck squamous cell carcinoma." (PMID 30918060, 2019). "Invasion/migration, proteins involved in epithelial-to-mesenchymal transition (EMT), and expression of MMP-2 and HIF-1α were quantified in the CSC subpopulations of two head-and-neck squamous cell carcinoma (HNSCC) cell lines irradiated with X-rays or C-ions." (PMID 30987217, 2019). "Consistently, MMP-2, not FAK, serves as an independent prognostic factor in head and neck squamous cell carcinomas." (PMID 33321813, 2020). "Moreover, in head and neck squamous cell carcinoma (HNSCC), TTP down-regulation enhances the stability of mRNAs, promotes IL-6 and VEGF secretion and significantly increases cellular invasion in cancers by increased secretion of IL-6 and MMP-2/9." (PMID 30850014, 2019).
osteoarthritis (28 papers, 2006 to 2026). A noninflammatory degenerative joint disease occurring chiefly in older persons, characterized by degeneration of the articular cartilage, hypertrophy of bone at the margins and changes in the synovial membrane. "A subsequent comparative analysis parallels these 9 pivotal osteoarthritis-associated genes with 3 previously identified chondrocyte-specific targets—namely, Mmp2, Hsd11b1, and Pla2g2a—revealed substantial overlap with Pla2g2a." (PMID 40880649, 2025). "In osteoarthritis, the rs243849 polymorphism has been linked to increased MMP-2 levels, accelerating cartilage degradation." (PMID 39769454, 2024). "MMP-2 is tightly associated with inflammatory states such as osteoarthritis; besides, MMP-2 protects from hypertensive heart disease by suppressing the transcription and activity of 3-hydroxy-3-methylglutaryl-CoA reductase in the early stages of the hypertensive response." (PMID 32454796, 2020). "MMP-13, a matrix metalloproteinase expressed in osteoarthritis cartilage and causes collagen degradation, was upregulated in σB treated group MMP2, was upregulated in both ARV and σB treated group, is known as the most potent type II collagen degrading protein and along with MMP-13." (PMID 29731966, 2018). "Within the osteoarthritis test groups, the O + B100 and O + M groups saw a marked reduction in MMP-2 mRNA levels compared to the OC group." (PMID 38542192, 2024). "Individuals carrying the T allele have been shown to exhibit higher MMP-2 activity, which can exacerbate conditions characterized by excessive ECM degradation, such as cancer metastasis, osteoarthritis, and CVD." (PMID 39769454, 2024). "These encouraging results promote further investigation to validate the utilization of MMP-2 siRNA as ‘‘molecular switch’’ able to counteract osteoarthritis." (PMID 36904410, 2023). "Expression of gelatinases such as MMP-2 (gelatinase A) and MMP-9 (gelatinase B) has been shown to associate with the pathogenesis of osteoarthritis." (PMID 32189997, 2020). "Additionally, NO can be beneficial in the treatment of osteoarthritis by strongly inhibiting the expression of gelatinases like MMP-2 and MMP-9, which play a significant role in cartilage and bone destruction." (PMID 37623223, 2023). "In the pathogenesis of osteoarthritis (OA), MMP-2, -8, -9 and -13 are of vital importance." (PMID 35682922, 2022). "MMP-2 was also significantly detectable in late stage osteoarthritis." (PMID 29731966, 2018). "In our MIA-induced osteoarthritis animal model, BSRE administration diminished the production and content of MMP-3 and -13 in the serum and suppressed the expression of MMP-2, -3, and -13 mRNA in the synovium." (PMID 38542192, 2024). "These encouraging results promote further investigation on the described nanocomplex to validate MMP-2 siRNA as ‘‘molecular switch’’ able to support ECM homeostasis and counteract osteoarthritis." (PMID 36904410, 2023). "Significant reductions in the serum levels of MMP-2 and MMP-9 indicate that JBT has a role to play in preventing osteoarthritis." (PMID 36062127, 2022). "We analyzed MMP expression to assess the anti-osteoarthritis effects of LI73014F2 and showed that a 50 mg/kg dose of the compound significantly reduced MMP-2, MMP-3, and MMP-13 levels." (PMID 33238379, 2020). "RT-PCR showed that the expressions of CD147, MMP-2 and MMP-9 mRNA was higher in RA FLS than in osteoarthritis FLS." (PMID 16507143, 2006). "Future research will focus on analyzing the protein expression of MMP-2, MMP-3, MMP-9, and MMP-13 to more fully elucidate the molecular mechanisms by which BSRE impacts osteoarthritis progression, providing valuable insights for developing more effective therapeutic strategies." (PMID 38542192, 2024). "However, in the articular cartilage, MMP-2 and MMP-9 have been studied in osteoarthritis (OA) and normal cartilage samples." (PMID 36278554, 2022).
osteoarthritis (continued). "Many proteolytic enzymes such as MMP-2, MMP-9, or cathepsin-K were involved in bone remodeling process, and MMPs were key degrading enzyme expressed in either physiological or pathological conditions including osteoarthritis, and osteoporosis." (PMID 32165922, 2020). "Similarly, MMP-13, MMP-3, MMP-2, and MMP-9 increased in the cell line model of osteoarthritis." (PMID 32189997, 2020). "Similarly, in osteoarthritis, PEA therapy significantly reduced levels of pro-inflammatory mediators, including leukotriene B4, tumor necrosis factor-α, interleukin-1β, and prostaglandin E2, as well as cartilage-degrading enzymes such as matrix metalloproteinase-2 (MMP-2), MMP-3, MMP-9, and MMP-13." (PMID 39433509, 2024).